BCL2 (BCL2 apoptosis regulator)
Diseases named in the same sentence as BCL2 in open-access papers (continued):
Sharing a sentence is not in itself a finding about the gene and the disease.
leukemia (continued). "Overexpression of antiapoptotic proteins such as Bcl-2, Bcl-XL, and Mcl-1 has found to be associated with drug resistance in human tumor cell lines, including leukemia and NHL cells." (PMID 33312200, 2020). "Increased leukemia development was observed also in Eμ-Myc transgenic mice upon genetic disruption of one BIM (BCL2 pro-apoptotic protein) allele." (PMID 30941349, 2019). "In CLL, the most common leukemia in humans, overexpression of BCL-2 originates from the loss of repression by miRNA 15/16." (PMID 29747654, 2018). "BCL-2 is also overexpressed in both acute and chronic leukemias where loss of microRNAs regulating BCL-2 expression are common." (PMID 29732004, 2018). "Damage to the BCL-2 gene has been identified as a cause of a number of cancers, including melanoma, breast, prostate, leukemia, and lung cancer." (PMID 27462919, 2016). "Treatment of doxorubicin-resistant human leukemia cells (K562/Adr) with withaferin-A resulted in caspase-mediated apoptosis induction, which was associated with decreased expression of Bcl-2, Bim and p-Bad." (PMID 26959007, 2016). "Consistent with this, Bcl‐2 family molecular signatures, including Bcl‐xl, Bcl‐2, Noxa, and Bcl‐w, correctly predict susceptibility to N of 70% of small‐cell lung cancers and 81% of leukemias and lymphomas." (PMID 26711051, 2016). "BCL-2 has been previously implicated in the pathogenesis of MLLr leukemias, and disruption of MLL-fusion-driven BCL-2 expression has been proposed as a major mechanism of action for the bromodomain inhibitor I-BET151." (PMID 26711339, 2015). "Our preclinical data suggest that co-targeting of DYRK1A and menin or BCL2 has particular activity against this high-risk leukemia subtype that may warrant clinical investigation in patients in the future to address issues of chemoresistance and relapse risk." (PMID 40148558, 2025). "Interestingly, VEN-insensitive samples showed significantly higher synergy scores thus indicating a clearly higher susceptibility of VEN-resistant leukemias to combined BCL-2 and OxPhos inhibition." (PMID 38961053, 2024). "MCL1 dependency on leukemia blasts is associated with resistance to BCL2 inhibition by VEN." (PMID 37065864, 2023). "Treatment response to the BCL2 inhibitor venetoclax together with hypomethylating agents may be short-lived with leukemia relapse as the major cause of treatment failure." (PMID 36293442, 2022). "Investigations using apoptosis-resistant BCR-ABL+ mice suggest BCL-2 mutations in myeloid progenitors may be critical in the transition of BCR-ABL+ leukemias to advanced stage disease." (PMID 33637708, 2021). "Several potential mechanisms of acquired venetoclax resistance in AML and other leukemias are discussed, including modulation of expression levels of the BCL2 target and compensatory upregulation of BCL2 paralogs and acquired mutations in BCL2 that affect drug binding." (PMID 34532658, 2021). "Previous studies reported that berbamine, the lead compound of BBD24, suppressed the expression of multidrug-resistance protein (MDR1) and Bcl-2 in K562 leukemia cells, caused depolarization of the mitochondrial membrane and decreased the membrane potential of HepG2 tumor cells." (PMID 32713851, 2020). "Interestingly, functional dependence of the leukemia cells on BCL-2 (BAD-HRK priming) was strongly associated with in vivo VEN activity, and importantly, showed high sensitivity and specificity in predicting preclinical in vivo antileukemia activity of VEN." (PMID 31358732, 2019). "BCL2 is an important driver of leukemia and referred to as a driver mutation." (PMID 29697361, 2018). "The inhibitors of BCL2 show efficacy in pre-clinical and early phase clinical trials of myeloma, small-cell-lung cancer, high-risk B cell non-Hodgkin lymphoma, and leukemia." (PMID 27008505, 2016).
leukemia (continued). "Western blot analyses were performed to determine whether vinflunine resistance in P388 leukaemia cells was associated with changes in relative endogenous Bcl-2, Bfl-1/A1, Bax, and Bcl-xL expression." (PMID 11857026, 2002). "Moreover, recognizing the heightened susceptibility of KMT2A-rearranged (KMT2Ar) leukemias to apoptosis induction through BCL2 inhibition, recent observations have shown synergistic activity in models of KMT2Ar or NPM1-mutated (NPM1mt) leukemia with dual Bcl-2 and menin inhibition." (PMID 38673842, 2024). "A recent report illustrated the capacity of 3L3-L1 preadipocytes to protect human leukemia cell lines from chemotherapeutic agents, an effect which was independent of cell contact and associated with the increased expression of antiapoptotic factors Pim-2 and Bcl-2." (PMID 32906729, 2020). "Among the active cyanobacteria extracts, L26-O presented the highest apoptosis-inducing activity, could partly overcome the chemotherapy resistance caused by the Bcl-2 protein and was highly potent also against the human leukemia patient-derived cell line, Molm13." (PMID 24705501, 2014). "In another study, 3L3-L1 adipocytes were shown to protect human leukemia cell lines from vincristine, nilotinib, daunorubin and dexamethasone, an effect which was independent of cell contact and associated with the increased expression of anti-apoptotic factors Pim-2 and Bcl-2." (PMID 22949815, 2012). "Building on this achievement, the development of venetoclax, a highly selective BCL-2 inhibitor, marked a major breakthrough, demonstrating potent pro-apoptotic activity and clinical efficacy in several leukaemia subtypes." (PMID 41937490, 2026). "Our study found that CTSD knockdown promoted apoptosis in leukemia cells by inducing the degradation of the anti-apoptosis proteins BCL2, BCL-XL, and MCL1." (PMID 40796615, 2025). "Previous studies have reported that Stat1 activation enhances bcl2 expression and promotes leukemia." (PMID 39929806, 2025). "The developed peptidomimetic downregulated the MYB-bound BCL2 enhancer, leading to the downregulation of BCL2 expression and apoptosis of leukaemia cells." (PMID 40243822, 2025). "It was reported to affect cellular pathways, such as the modulation of Bcl-2 anti-apoptotic protein, and the induction of autophagy-related protein in human leukemia cells." (PMID 40508060, 2025). "The role of aza has been described in the literature as a synergistic inhibitor of the proteins MCL1 and BCL-xL, thereby increasing the dependence of leukemia cells on BCL2." (PMID 40973765, 2025). "Appropriate levels of BAX/BAK bound by high levels of BCL-2 indicate a BCL-2 dependence in the leukemia cell, mediating effective cell death induction upon venetoclax treatment." (PMID 40234615, 2025). "Anti-apoptotic BCL2 family members, including BCL2, BCL-XL, and MCL1, suppress apoptosis and are upregulated in cancer cells, including leukemia cells, where their expression is associated with poor prognosis." (PMID 40796615, 2025). "Inhibiting BCL-2 can target oxidative phosphorylation and selectively eliminate leukemia stem cells." (PMID 39862423, 2025). "Bcl-2 is the most representative apoptosis-inhibiting gene and is abundantly expressed in malignant tumors such as gastric cancer and leukemia." (PMID 40236708, 2025). "Our results demonstrate that KMT2A-R ALL requires DYRK1A for normal cell proliferation and dual inhibition of DYRK1A and BCL2 decreases leukemia progression in KMT2A-R ALL PDX models." (PMID 40148558, 2025). "As emphasized in our study, dual targeting of BCL-2 effectively eliminates leukemia cells in both in vitro and in vivo experiments." (PMID 39862423, 2025). "Includes BCL2 inhibitors, informed by efficacy in related stem-cell-derived leukemias such as ETP-ALLand, based on AML studies." (PMID 41477275, 2025).
leukemia (continued). "In fact, over-expression of anti-apoptosis proteins Bcl-2 and Mcl-1 served as the hallmarks of leukaemia and myeloma; for this reason, the discovery of new drugs that can inhibit the expression of Bcl-2 and Mcl-1 is important in curing leukemia." (PMID 40141366, 2025). "Targeting Bcl-2 family proteins is a proven strategy to tackle apoptosis-resistant cancers, and the Bcl-2 inhibitor venetoclax is currently applied for the therapy of leukemias (CLL, ALL)." (PMID 39935431, 2025). "Venetoclax is a suitable candidate for treating various leukemia due to its BCL2 inhibitory properties; the increased BCL2 level in patients correlates with therapy resistance." (PMID 38594732, 2024). "Among the Bcl–2 AUBPs we identified Zeta-Crystallin (CryZ), demonstrating its role in increasing Bcl-2 mRNA stability in human leukaemia cell lines." (PMID 39021835, 2024). "In mice bearing Ph+ ALL-674 or ALL-1222 cells, palbociclib plus BCL2 inhibitor (sabutoclax) significantly decreased the peripheral leukemia load." (PMID 38835346, 2024). "Another study revealed that combining ruxolitinib with Bcl-2/Mcl-1 inhibitors exhibited a synergistic killing effect on leukemia cells." (PMID 38273387, 2024). "To verify these findings in the clinic, we analyzed the mRNA expression of BCL2 in seven APL primary mononuclear cell cultures collected from leukemia patients at disease presentation by quantitative RT-PCR (qRT-PCR)." (PMID 39598439, 2024). "For example, overexpression of anti-apoptotic proteins such as Bcl-2 can inhibit mitochondrial membrane permeabilization, enabling leukemia cells to avoid apoptosis." (PMID 39273651, 2024). "It has been proven that HB at the same tested concentrations (0.2 and 0.4 mg/mL) reduces BCL-2 expression in UT-7 human leukemia cells." (PMID 38930984, 2024). "Melittin can also induce Bcl2-dependent and caspase-3-dependent apoptosis in U937 leukemia cells by inhibiting the AKT signaling pathway." (PMID 38445441, 2024). "Up-regulation of Bcl-2 and other anti-apoptotic genes (Bcl-xl, Bcl-2L10, Bag3 and Iap2/Birc3) have been also documented in Bu-resistant leukemia cell lines, which are capable of evading busulfan mediated G2-arrest and apoptosis." (PMID 38321093, 2024). "In the context of leukemia, NF-κB activation leads to the transcription of anti-apoptotic genes, such as BCL-2 and BCL-XL, which help leukemia cells evade apoptosis, induced by chemotherapeutic agents." (PMID 39572459, 2024). "Their experiments further declare that,over-expression of Bcl-2 attenuates naringenin induced Bax translocation andcytochromeC release to cytosol in human leukemia U937 cells." (PMID 39474581, 2024). "By integrating chemotherapy and/or BCL-2 inhibition, these regimens aim to dismantle leukemia survival networks more comprehensively." (PMID 39682203, 2024). "Dual Inhibitors: Ongoing research has focused on developing compounds that can simultaneously inhibit multiple anti-apoptotic proteins (e.g., dual Bcl-2/Bcl-XL inhibitors) to prevent resistance and promote sustained apoptosis in leukemia cells." (PMID 39273651, 2024). "The therapeutic targeting of Bcl-2 in leukemia emerged following the elucidation of its crucial role in evading apoptosis." (PMID 38675444, 2024). "The overexpression of Bcl-2 is particularly evident in leukemias, lymphomas, especially follicular lymphoma (FL) and chronic lymphocytic leukemia CLL), as well as in some solid tumors, such as breast cancer, lung cancer, and melanoma." (PMID 39684550, 2024). "Venetoclax, an inhibitor of B-cell lymphoma-2 protein (BCL2), has been shown to selectively target leukemia stem cells (LSCs) due to their overexpression of BCL2." (PMID 38339283, 2024).
leukemia (continued). "An important reason for the high relapse rate in leukemia is the upregulation of antiapoptotic proteins (such as BCL‐2 and BCL‐xL), which prevents apoptosis and thereby promotes the survival of LSCs during treatment." (PMID 39445003, 2024). "Venetoclax, a BCL-2 inhibitor with high oral bioavailability, has significantly improved the treatment landscape for leukemia, particularly CLL/SLL and AML, by overcoming anti-apoptotic mechanisms and achieving high remission rates and sustained responses." (PMID 38675444, 2024). "This, in turn, can alleviate leukemia resistance to TKIs therapy by reducing the stability of BCL-2." (PMID 39095902, 2024). "In KMT2Ar leukemias, BRD4 is often associated with super-enhancers that drive the expression of oncogenes such as MYC, BCL2, and CDK6, which are vital for leukemic cell survival and proliferation." (PMID 39682203, 2024). "AZA plays the predominate demethylating role, whereas VEN is primarily a B-cell lymphoma 2 (BCL-2) inhibitor that selectively inhibits the survival signaling pathway of leukemia cells." (PMID 38510975, 2024). "Venetoclax stands out for its role in inhibiting Bcl-2, a protein that typically prevents apoptosis and is overexpressed in many patients with leukemia." (PMID 39273651, 2024). "YBX1 interacts with m6A readers IGF2BPs through its conserved cold shock domain to indirectly bind m6A‐modified mRNA, thereby enhancing the stability of apoptosis‐related genes MYC and BCL2, which in turn sustains the function of leukemia cells." (PMID 39445003, 2024). "Lopez-Berestein and his colleagues worked with liposomal ASOs targeting Grb2 (BP1001, Prexigebersen) and Bcl-2 oncogenes for breast cancer and leukemia cells, respectively." (PMID 39272802, 2024). "The Loucy cell line, derived from an immature ETP leukemia, demonstrated high sensitivity to Bcl-2 inhibition, with an IC50 of 13.9 nM." (PMID 39684550, 2024). "First designed and tested for leukemia in 1990, BCL-2-targeting ASOs are arguably the most extensively studied NATs in myeloid leukemias." (PMID 38424137, 2024). "According to the analysis, there was a correlation between the Bcl-2-AA genotype and a higher likelihood of leukemia." (PMID 37232720, 2023). "Bcl-2 is an anti-apoptotic protein that protects leukemia cells and LSCs from therapeutic agent-induced apoptosis." (PMID 37644011, 2023). "Most importantly, we found that sorafenib can inhibit apoptosis by activating the JAK-STAT3 pathway to promote the expression of BCL2 in leukemia cells." (PMID 37887047, 2023). "Palytoxin-induced dephosphorylation of Bcl-2 further exacerbated the proapoptotic effect of Mcl-1 and Bcl-xL degradation in a range of leukemia cell lines." (PMID 37103372, 2023). "Venetoclax is a B cell lymphoma-2 (BCL-2) inhibitor used to treat various types of leukemia and is but actively being investigated as a potential treatment for DLBCL due to the role of BCL-2 in this malignancy." (PMID 36671496, 2023). "Venetoclax was found to be more specific for BCL-2 and has shown success as part of a drug cocktail in combating leukemias." (PMID 36795726, 2023). "Here, we demonstrate that combined inhibition of Bcl-2 by venetoclax and activation of PPARα by chiglitazar has synergistic anti-leukemia activity against LSC-like cell lines (KG-1α and Kasumi-1) and CD34+ primary AML cells while sparing normal cells in vitro." (PMID 37644011, 2023). "Leukemia cells from all 23 patients expressed BCL-2 and median percentage of BCL-2 expression in leukemia cells was 92.7% (range: 15.1–98.0)." (PMID 36629738, 2023). "As a specific inhibitor of Bcl-2, venetoclax is very potent in inducing apoptosis in leukemia cell lines depending on Bcl-2." (PMID 37644011, 2023).
leukemia (continued). "The overexpression of BCL-2 by AML and leukemia stem cells (LSC) has been implicated in accelerated disease progression and chemotherapy resistance." (PMID 37046645, 2023). "It was shown that leukemias are dependent on the continuous function of either MCL-1 or BCL-2 for survival." (PMID 37108344, 2023). "It has been observed that the Bcl-2-938 C>A gene variation is statistically related to overall survival and remission rates in leukemia." (PMID 37232720, 2023). "A concentration-dependent decrease in leukemia cell count was observed 24 h and 48 h after application of the BCL-2 inhibitors alone." (PMID 37108344, 2023). "Navitoclax, a BCL-2 inhibitor, have been demonstrated as a single agent or in combine with other drugs to successfully eradicate leukemia cells." (PMID 37138869, 2023). "DLST-altered cell lines were more sensitive to 7 approved drugs, among these obatoclax mesylate, a BCL2 inhibitor that reduces OXPHOS in human leukemia stem cells." (PMID 36634214, 2023). "β-Sitosterol has been reported to promote apoptosis in human gastric cancer SGC 7901 cells and human leukemia U937 cells by upregulating the expression of cleaved-caspase 3 and Bax proteins, while downregulating the expression of Bcl-2 protein." (PMID 38028434, 2023). "The median ratio of the mean fluorescence intensity (MFI) of BCL-2 level in leukemia cells relative to nucleated erythrocytes was 11.7-fold higher (range: 3.0–23.2)." (PMID 36629738, 2023). "Venetoclax (VCX) is a BCL2 inhibitor approved for treating B cell-derived leukemia, including chronic lymphocytic leukemia (CLL)." (PMID 40395294, 2023). "The advent of targeted therapies for leukemia, such as the first-in-class, orally bioavailable BCL-2 inhibitor, venetoclax, has changed the therapy landscape; however, even these new agents are not without shortcomings." (PMID 36980769, 2023). "Our results indicate significant differences in the occurrence of Bcl-2-938 C>A rs2279115 CC, CA, and AA genotypes between leukaemia patients and healthy controls (p = 0.025)." (PMID 37232720, 2023). "ABC transporters inhibitors like Verapamil to overcome CSCs’ efflux pump-mediated resistance, BCL-2 inhibitors in leukemia to counter apoptosis resistance." (PMID 37886168, 2023). "KMT2A::AF4 directly regulates BCL2 gene expression by promoting increased H3K79me2/3 levels in the BCL2 gene vicinity leading to a BH3-dependance in KMT2A-rearranged leukaemia." (PMID 37189994, 2023). "The downregulation of Mcl-1 sensitizes AML to Bcl-2 inhibitor-induced leukemia cell killing, and we have also reported a highly synergistic effect of venetoclax with Mcl-1 inhibition recently." (PMID 36865133, 2023). "The proliferation of leukemia cells and inducing apoptosis has been inhibited by Circ_PTK2 silencing with reducing cyclin D1 expression and Bcl-2/Bax level regulation." (PMID 37124518, 2023). "The Western blot results further confirmed that BCL2 was significantly upregulated in leukemia cells treated with sorafenib." (PMID 37887047, 2023). "Genetic and pharmacologic ABCC1 inactivation potentiates the anti-leukemic effects of BCL-2 inhibitors and efficiently re-sensitizes Venetoclax-resistant leukemia cells." (PMID 37726279, 2023). "Targeting FLT3 and Bcl-2 and/or Mcl-1 simultaneously resulted in a synergistic pro-apoptotic effect in FLT3mutant leukemia cells." (PMID 36865133, 2023). "Adenosine also induced apoptosis in different cancer types such as breast, leukaemia, gastric, colon, melanoma, and head and neck cancer cell lines, and suppressed BCL-2 expression." (PMID 37193964, 2023). "Application of this method in a large cohort of samples from the HOVON141 clinical trial validated differential Bcl-2 member expression in these two circulating leukemia fractions." (PMID 37100883, 2023). "In particular, lymphomas and leukemias are regularly found to have upregulation one or more of the proteins BCL-2, MCL-1, and BCL-xL." (PMID 36795726, 2023).